ATL1 (atlastin GTPase 1)
Description:
Atlastin-1 (ATL1) is a membrane-anchored GTPase that mediates the GTP-dependent fusion of endoplasmic reticulum (ER) membranes, maintaining the continuous ER network. It facilitates the formation of three-way junctions where ER tubules intersect. Two atlastin-1 on neighboring ER tubules bind GTP and form loose homodimers through the GB1/RHD3-type G domains and 3HB regions. Upon GTP hydrolysis, the 3HB regions tighten, pulling the membranes together to drive their fusion. After fusion, the homodimer disassembles upon release of inorganic phosphate (Pi). Subsequently, GDP dissociates, resetting the monomers to a conformation ready for a new fusion cycle. May also regulate more or less directly Golgi biogenesis. Indirectly regulates axonal development (By similarity).
Synonyms: ATL-1; SPG3; SPG3A; FSP1; AD-FSP; HSN1D; atlastin1
Tractability: Small molecule: a structure with a bound ligand is known; it has a high-quality binding pocket. Antibody: UniProt predicts a signal peptide or a membrane-spanning region. PROTAC: ubiquitination databases record sites on it; its protein half-life has been measured.
Gene: Protein-coding gene on chromosome 14 (50,532,509 to 50,634,017, forward strand). Ensembl gene ENSG00000198513.
Subcellular location: Endoplasmic reticulum membrane; Golgi apparatus membrane; Cell projection, axon
Gene Ontology:
Molecular function: GTPase activity; GTPase-dependent fusogenic activity; identical protein binding; protein binding; GTP binding
Biological process: endoplasmic reticulum membrane fusion; endoplasmic reticulum tubular network membrane organization; axonogenesis; endoplasmic reticulum organization; protein homooligomerization
Cellular component: endoplasmic reticulum; endoplasmic reticulum membrane; endoplasmic reticulum tubular network membrane; Golgi membrane; endoplasmic reticulum tubular network; Golgi apparatus; Golgi cis cisterna membrane; axon; cytoplasm; endoplasmic reticulum subcompartment
Genetic constraint (gnomAD): Loss-of-function variants: 24 observed, 59.23 expected, observed/expected ratio (o/e) 0.41, 90% interval 0.29 to 0.57. The upper end of that interval is the gene's LOEUF score, 0.57, which puts it in group 2 of 6, group 1 being the genes least tolerant of losing a copy. Missense variants: 359 observed, 621.59 expected, observed/expected ratio (o/e) 0.58, 90% interval 0.53 to 0.63. Synonymous variants: 208 observed, 223.78 expected, observed/expected ratio (o/e) 0.93, 90% interval 0.83 to 1.04.
Gene-disease validity (ClinGen):
ClinGen rates the evidence that ATL1 causes each of these diseases.
neuropathy, hereditary sensory, type 1D (autosomal dominant): Definitive.
Homologues: Orthologues: chimpanzee ATL1 (99% identical), macaque ATL1 (99% identical), rabbit ATL1 (99% identical), guinea pig ATL1 (98% identical), pig ATL1 (98% identical), dog ATL1 (98% identical), rat Atl1 (97% identical), mouse Atl1 (97% identical), tropical clawed frog atl1 (89% identical), zebrafish atl1 (80% identical), Drosophila melanogaster atl (51% identical). Paralogues in human: ATL2 (65% identical), ATL3 (59% identical), GBP1 (22% identical), GBP3 (21% identical), GBP4 (21% identical), GBP2 (21% identical), GBP6 (21% identical), GBP7 (20% identical), GBP5 (20% identical), RNF112 (20% identical).
Diseases named in the same sentence as ATL1 in open-access papers:
ATL1 is named in the same sentence as 59 diseases in open-access papers, as found by Europe PMC text mining. Sharing a sentence is not in itself a finding about the gene and the disease. The quoted sentences say what the papers report.
hereditary spastic paraplegia (31 papers, 2010 to 2025). Hereditary spastic paraplegias (HSP) comprise a genetically and clinically heterogeneous group of neurodegenerative disorders characterized by progressive spasticity and hyperreflexia of the lower limbs. "Deletion of ATL results in long unbranched ER tubules in cells, and mutation of human ATL1 is linked to hereditary spastic paraplegia." (PMID 31239341, 2019). "ATL1 gene mutations are thought to be the most common cause of hereditary spastic paraplegia with an AAO < 10 years." (PMID 28396731, 2017). "In humans, mutations in ATL1 cause hereditary spastic paraplegia (HSP), a neurodegenerative disease." (PMID 28287394, 2017). "Mutations in human ATL1 cause a neurodegenerative disease known as hereditary spastic paraplegia (HSP) and mutations in RHD3 lead to defects in plant growth and short and wavy root hairs, suggesting a physiological significance of ER network formation." (PMID 25773277, 2015). "Interestingly, an updated study indicates that MN-specific CPT1C can interact with atlastin-1 encoded by the ATL1 gene, which is mutated in hereditary spastic paraplegia, a kind of motor neuron degenerative disorder." (PMID 33339220, 2020). "Mutations of ATL1 in humans result in defective neurite outgrowth and cause hereditary spastic paraplegia (HSP)." (PMID 38774354, 2024). "Mutation of the ATL1 gene is one of the most common causes of hereditary spastic paraplegia (HSP), a group of genetic neurodegenerative conditions characterised by distal axonal degeneration of the corticospinal tract axons." (PMID 38851544, 2024). "ATL1 is one of the genes that is mostly found to be mutated in the early-onset forms of autosomal dominant hereditary spastic paraplegia (HSP)." (PMID 35188422, 2022). "Mutations identified in ATL1 have been linked to autosomal dominant hereditary spastic paraplegia (HSP)." (PMID 34571977, 2021). "ATL1 mutations are linked to the human disease hereditary spastic paraplegia (HSP), which is characterized by progressive spasticity and weakness of the lower limbs due to retrograde degeneration of corticospinal axons." (PMID 31239341, 2019). "One of the main causes of hereditary spastic paraplegia (HSP) are heterozygous mutations in Atl1, which has an age of onset ~21 years." (PMID 28893375, 2017). "Hereditary spastic paraplegia (HSP), a group of disorders caused by mutations in genes that regulate axonal transport (e.g., SPAST, ATL1), represents another area of genomic medicine." (PMID 40806492, 2025). "Mutations in ER-shaping proteins such as Spastin, ATL1, RTN2 or REEP1 that couple the tubular ER network with microtubule dynamics cause hereditary spastic paraplegia." (PMID 35650592, 2022). "ATL1, RTN2, SPAST and REEP1 are the causative genes of hereditary spastic paraplegia (HSP)." (PMID 29310658, 2018). "This notion is strengthened by the fact that mutation in ER morphology and degradation-regulating proteins, including ATL1, ATL3, REEP, and FAM134, are common causes of the motor neuron diseases hereditary spastic paraplegia (HSP) and hereditary sensory and autonomic neuropathy (HSAN)." (PMID 36960757, 2024). "Variants in proteins involved in microtubule dynamics (SPAST), axonal maintenance (ATL1) and transport (KIF1A) are among the most common genetic etiologies both of cerebral palsy mimicries and of hereditary spastic paraplegia (HSP)." (PMID 40095113, 2025).
Spastic paraplegia (14 papers, 2010 to 2025). Complete loss of the ability to move the lower limbs accompanied by spasticity of the lower limbs. "This autosomal-dominant-inherited motor disorder is caused by heterozygous variants in the ATL1 gene which usually presents as a pure childhood-onset spastic paraplegia." (PMID 39003427, 2024). "Here we have identified a novel mutation in ATL1 that causes a complex form of spastic paraplegia involving all four extremities of the proband." (PMID 34808209, 2022). "n.44, 45, and 59) carry the same 14q22.1 duplication encompassing ATL1, one of the causative genes of spastic paraplegia." (PMID 35762097, 2022). "ATL1 gene was commonly thought to be associated with pure spastic paraplegia manifesting as lower limb spasticity, decreased vibration sense in the lower limbs, and sphincter disturbances." (PMID 28396731, 2017). "In conclusion, we reported the mutational spectrum of the SPAST and ATL1 genes in a large cohort of Spanish patients with spastic paraplegia." (PMID 20932283, 2010). "In comparison to ATL1 in which mutations result in spastic paraplegia, which emphasizes the importance of a branched ER network in neuronal axons (and references therein), ATL2 may be important in filipods and other mechanisms involved in cellular migration." (PMID 37628611, 2023). "In a large cohort of Spanish patients with spastic paraplegia, SPAST and ATL1 mutations were found in 15% of the cases." (PMID 20932283, 2010). "Mutations in ATL1 and ATL3 cause spastic paraplegia and hereditary sensory neuropathy." (PMID 30666337, 2019). "Genetic tests performed before WES excluded Huntington’s disease (IT15), spinal muscular atrophy (SMN1), spinal bulbar muscular atrophy (AR), primary torsion dystonia (DYT1), and the common forms of spastic paraplegias (SPG4, REEP1, ATL1, SPG7)." (PMID 25957632, 2015). "After that, 3 cases of spastic paraplegia were found in patients (No. 2, 22, and 26) with responsible genes including (HACE1, ATL1, AP4M1), respectively, and two cases of cerebellar ataxia in patients (No. 14 and 43), whose responsible genes were SNX14, TDP2, respectively." (PMID 34540776, 2021).
Ataxia (7 papers, 2015 to 2025). Ataxia refers to impaired coordination of voluntary muscle movement. "Interestingly, mutations in the ATL1, SPAST, RAB7A or KATNB1 genes have been previously associated with diseases presenting with hyperreflexia, sensory axonal neuropathy or sensory impairment among other signs, which overlap with clinical signs identified in this new ataxia subtype in our family." (PMID 35310830, 2022).
hereditary sensory and autonomic neuropathy (4 papers, 2019 to 2024). An instance of sensory peripheral neuropathy that is caused by an inherited modification of the individual's genome. "Mutations in ATL1, encoding for atlastin-1,have been found as causative in a subtype of HSP, SPG3A, and in hereditary sensory and autonomic neuropathy (HSAN)." (PMID 34359848, 2021). "While the HSP-associated mutation presented here demonstrates a novel gain-of-function disease mechanism in ATL1, a recent study characterized two gain-of-function mutations in ATL3 (Y192C and P338R) that had been identified in hereditary sensory neuropathy patients." (PMID 34808209, 2022). "In addition to their role in HSP, familial mutations in ATL1 and ATL3 have been found to cause hereditary sensory neuropathy (HSN), another neurodegenerative disorder affecting sensory neurons." (PMID 34808209, 2022).
hereditary spastic paraplegia 3A (3 papers, 2016 to 2023). Any hereditary spastic paraplegia in which the cause of the disease is a mutation in the ATL1 gene. "According to the Human Gene Mutation Database (HGMD) more than a hundred mutations have been reported in ATL1, causing either spastic paraplegia 3 (SPG3A; OMIM #182600) or hereditary sensory neuropathy type 1D (HSN1D; OMIM #613708)." (PMID 37371660, 2023).
melanoma (3 papers, 2021 to 2023). A malignant, usually aggressive tumor composed of atypical, neoplastic melanocytes. "At the same time, ATL-1 can also induce apoptosis of human melanoma cells by triggering the production of nitric oxide (NO) and ROS." (PMID 37004014, 2023). "Studies have found that ATL-1 has strong anti-tumor effects on leukemia, bladder cancer and melanoma." (PMID 36686743, 2022). "ATL-1 was found to inhibit melanoma and colorectal cancer cell proliferation via the JAK2/STAT3 or AKT/mTOR signaling pathway." (PMID 34692516, 2021). "ATL-1 has antitumor effects on a variety of cancers, including colon cancer, breast cancer, melanoma, ovarian cancer and gastric cancer." (PMID 34692516, 2021). "It was also confirmed in the mouse melanoma model that ATL-1 could inhibit tumor growth and the M2 TAMs markers isolated from mouse melanoma were significantly reduced." (PMID 37004014, 2023). "ATL-1 has a significant inhibitory effect on leukemia, bladder cancer and melanoma." (PMID 36686743, 2022).
autosomal dominant pure HSP (2 papers, 2017 to 2020). "First, we find that most HSPs-SPG3A patients exhibiting early AAO and autosomal dominant pure spastic paraplegia there have a wide mutational spectrum associated with ATL1 gene mutations." (PMID 28396731, 2017). "Consistent with this, roles in lipid droplet size regulation have also been defined for spastin binding partner atlastin-1 (ATL1), mostly responsible for autosomal dominant pure HSP (SPG3A), although more complex HSP clinical presentations have also been described associated with ATL1 gene mutation." (PMID 31848577, 2020).
prostate carcinoma (2 papers, 2022 to 2024). A carcinoma that arises from epithelial cells of the prostate gland. "In this study, we also found that ATL-1 targeted inhibition of heat shock protein Hsp27 enhances the antitumor effect of cabozantinib chemotherapy in prostate cancer." (PMID 36686743, 2022). "In this study, the inhibitory effect of ATL-1 on tumor metastasis is related to Hsp27 in prostate cancer cells." (PMID 36686743, 2022). "ATL-1 also enhanced chemosensitization of cabozantinib in prostate cancer." (PMID 36686743, 2022). "However, there are few studies on the anti-tumor effect of ATL-1 on prostate cancer, and the molecular mechanism of its anti-tumor is still unclear." (PMID 36686743, 2022). "In this study, the effects of ATL-1 on human prostate cancer cells were studied." (PMID 36686743, 2022). "TUNEL results showed that silencing Hsp27 and ATL-1 treated could significantly promote the apoptosis of prostate cancer cells DU145 and PC-3 compared with the control group." (PMID 36686743, 2022). "Therefore, this study investigated the molecular mechanism of ATL-1 inhibiting the proliferation of prostate cancer cells." (PMID 36686743, 2022). "ATL-1 can inhibit the malignant evolution of prostate cancer cells by inhibiting Hsp27/eIF4E." (PMID 36686743, 2022). "Also, ATL-1 inhibited the further proliferation of prostate cancer and induced apoptosis." (PMID 38398019, 2024). "However, few studies have been done on the antitumor effect of ATL-1 on prostate cancer, and its molecular mechanism remains unclear." (PMID 36686743, 2022). "Qiao and Tian described that ATL-1 inhibits EMT by targeting Hsp27 and enhances the effect of cabozantinib in prostate cancer." (PMID 38398019, 2024). "MTT assay was used to detect the inhibitory effect of silencing Hsp27 and ATL-1 on DU145 and PC-3 proliferation of prostate cancer cells." (PMID 36686743, 2022). "qRT-PCR was used to detect the changes of apoptosis related genes caspase-3, PARP, Bax and Bcl-2 in prostate cancer cell DU145 and PC-3 after the effect of silencing Hsp27 and ATL-1 treated." (PMID 36686743, 2022). "qRT-PCR results showed that compared with the control group, ATL-1 could promote the expression of caspase-3, PARP and Bax in DU145 and PC-3 prostate cancer cells." (PMID 36686743, 2022).
temporal lobe epilepsy (2 papers, 2020 to 2022). A localization-related (focal) form of epilepsy characterized by recurrent seizures that arise from foci within the temporal lobe, most commonly from its mesial aspect. "Recently, significantly decreased ATL1 expression levels have been identified in the temporal lobe neocortex of patients with temporal lobe epilepsy (TLE)." (PMID 34808209, 2022).
aneurysm (1 paper, 2023). Bulging or ballooning in an area of an artery secondary to arterial wall weakening. "Our study found that abnormal expression of circ-ATL1, miR-455 and SIRT5 is correlated with the progression of IA in aneurysm patients." (PMID 36717793, 2023).
breast carcinoma (1 paper, 2021). "Apart from inhibiting TNBC cell migration via CTGF, ATL-1 downregulated the expression of CTGF in fibroblasts and decreased the ability of breast cancer cells to transform fibroblasts into cancer-associated fibroblasts (CAFs), which in turn increased the sensitivity of TNBC cells to paclitaxel." (PMID 34692516, 2021).
Intellectual disability (1 paper, 2021). "The one with the ATL1 mutation presented with severe, infant onset axonal CMT, with spasticity and profound intellectual disability." (PMID 34323022, 2021).
lung carcinoma (1 paper, 2013). "Therefore, ATL-1 may be an interesting potential apoptosis inducer that could be a candidate for the treatment of lung cancer in the future." (PMID 24172243, 2013).
pancreatic ductal adenocarcinoma (1 paper, 2023). An infiltrating adenocarcinoma that arises from the epithelial cells of the pancreas. "Previous studies have found that circ-ATL1 expression promoted the progression of pancreatic ductal adenocarcinoma by functioning as a miR-455 sponge." (PMID 36717793, 2023). "Hsa_circ_0102049 (also named circ-ATL1) has also been reported to have a critical role in mediating pancreatic ductal adenocarcinoma progression via targeting miR-455." (PMID 36717793, 2023).
psychosis (1 paper, 2020). "Two of those novel interactors, ATL1 and TRIM9 are shown to be associated with cognitive performance and psychosis respectively through GWAS." (PMID 32973177, 2020).
Sensory neuropathy (1 paper, 2022). Peripheral neuropathy affecting the sensory nerves. "Heterozygous pathogenic variants in the ATL1 gene are linked to HSP or sensory neuropathy." (PMID 35971119, 2022).
triple-negative breast carcinoma (1 paper, 2021). An invasive breast carcinoma which is negative for expression of estrogen receptor (ER), progesterone receptor (PR), and human epidermal growth factor receptor 2 (HER2). "In summary, our study demonstrated that ATL-1 could inhibit tumor cell migration via downregulation of CTGF in triple-negative breast cancer cells." (PMID 34692516, 2021).
Ureteral obstruction (1 paper, 2021). Obstruction of the flow of urine through the ureter. "As ATL-1 was reported to inhibit fibroblast-myofibroblast differentiation (FMD) and repress fibrosis development in unilateral ureteral obstruction kidneys." (PMID 34692516, 2021).